CABP1 (calcium binding protein 1)
Description:
Modulates calcium-dependent activity of inositol 1,4,5-triphosphate receptors (ITPRs). Inhibits agonist-induced intracellular calcium signaling. Enhances inactivation and does not support calcium-dependent facilitation of voltage-dependent P/Q-type calcium channels. Causes calcium-dependent facilitation and inhibits inactivation of L-type calcium channels by binding to the same sites as calmodulin in the C-terminal domain of CACNA1C, but has an opposite effect on channel function. Suppresses the calcium-dependent inactivation of CACNA1D (By similarity). Inhibits TRPC5 channels. Prevents NMDA receptor-induced cellular degeneration. Required for the normal transfer of light signals through the retina (By similarity).
Synonyms: CALBRAIN; HCALB_BR
Tractability: Small molecule: it has a high-quality binding pocket. Antibody: UniProt places it where antibodies can reach, with high confidence; its Gene Ontology location is reachable by antibodies, with high confidence.
Gene: Protein-coding gene on chromosome 12 (120,640,590 to 120,667,327, forward strand). Ensembl gene ENSG00000157782.
Subcellular location: Cytoplasm, cytoskeleton; Cytoplasm, perinuclear region; Cell membrane; Golgi apparatus; Postsynaptic density; Cytoplasm, cytoskeleton (Isoform L-CaBP1); Cytoplasm, cell cortex (Isoform S-CaBP1)
Pathways (Reactome):
Sensory Perception: Sensory processing of sound by inner hair cells of the cochlea
Gene Ontology:
Molecular function: calcium-dependent protein binding; protein binding; calcium channel regulator activity; calcium ion binding; enzyme inhibitor activity
Biological process: negative regulation of protein import into nucleus; phototransduction; visual perception
Cellular component: extracellular region; Golgi apparatus; Golgi membrane; plasma membrane; postsynaptic density; cell cortex; cytoskeleton; perinuclear region of cytoplasm
Genetic constraint (gnomAD): Loss-of-function variants: 15 observed, 24.1 expected, observed/expected ratio (o/e) 0.62, 90% interval 0.41 to 0.96. The synonymous counts are far from expectation, so gnomAD's model fits this gene poorly and the ratio says little. Missense variants: 371 observed, 378.44 expected, observed/expected ratio (o/e) 0.98, 90% interval 0.9 to 1.07. Synonymous variants: 198 observed, 156.36 expected, observed/expected ratio (o/e) 1.27, 90% interval 1.13 to 1.42.
Homologues: Orthologues: chimpanzee CABP1 (99% identical), macaque CABP1 (97% identical), pig CABP1 (95% identical), dog CABP1 (94% identical), mouse Cabp1 (88% identical), rat Cabp1 (88% identical), tropical clawed frog cabp1 (40% identical), zebrafish cabp1a (38% identical), zebrafish cabp1b (38% identical), Caenorhabditis elegans cal-1 (16% identical), Caenorhabditis elegans cal-3 (15% identical), Caenorhabditis elegans E02A10.3 (15% identical), and 9 more. Paralogues in human: CABP2 (33% identical), CABP5 (30% identical), CABP4 (28% identical), CALML3 (18% identical), CALM1 (17% identical), CALM2 (17% identical), CALM3 (17% identical), CABP7 (16% identical), CALN1 (16% identical), CETN1 (15% identical), CETN2 (15% identical), CETN3 (13% identical), and 8 more.
Diseases named in the same sentence as CABP1 in open-access papers:
CABP1 is named in the same sentence as 7 diseases in open-access papers, as found by Europe PMC text mining. Sharing a sentence is not in itself a finding about the gene and the disease. The quoted sentences say what the papers report.
dyslipidemia (1 paper, 2024).
glioblastoma (1 paper, 2023). The most malignant astrocytic tumor (WHO grade IV). "High levels of the calcium-binding protein 1 (CABP1), as detected after INPP4B overexpression in etoposide-resistant RB355 cells, were likewise revealed by Kaplan–Meier analysis of glioblastoma hub genes and was negatively associated with relapse-free survival of glioblastoma patients." (PMID 36993823, 2023).
neurological disorders (1 paper, 2012). "Moreover, some of the candidate genes have previously been linked to psychiatric and neurological disorders (e.g. RORB, HAP1, HCRTR1 and CABP1), further emphasising the potential importance of these candidate genes in the human brain." (PMID 22384057, 2012).
CABP1 also shares sentences with these, for which no sentence is quoted: Alzheimer disease (1 paper); diabetes (1); Down syndrome (1); Insulin resistance (1).